HDAC1 (histone deacetylase 1)
Diseases named in the same sentence as HDAC1 in open-access papers (continued):
Sharing a sentence is not in itself a finding about the gene and the disease.
ischemia (9 papers, 2016 to 2026). A hypoperfusion of the BLOOD through an organ or tissue caused by a PATHOLOGIC CONSTRICTION or obstruction of its BLOOD VESSELS, or an absence of BLOOD CIRCULATION. "HDAC1 has also been implicated in microglial inflammatory responses in ischemia, contributing to neuroinflammation and blood–brain barrier (BBB) breakdown." (PMID 40867911, 2025). "This systemic effect is at least in part associated with circulating EVs that increase their HDAC1 cargo following ischemia training, leading to reprogramming of the BM-Mono by downregulating Dhcr24 gene expression in recipient cells." (PMID 39404366, 2024). "In ischemia, specific HDAC isoforms (e.g., HDAC1, HDAC2, HDAC3, and HDAC6) have been implicated in microglial activation, glial reactivity, and disruption of immune balance." (PMID 40867911, 2025). "To determine the mechanism through which HDAC1 affects brain function in the pathogenesis of ischemia, we conducted a neurological severity score test and cylinder test to examine neurological function and spontaneous forelimb use." (PMID 34381129, 2021). "In the retina the deacetylase activity of HDAC1/2 displayed an increase in ischemia but a decrease following PC, which was closely correlated with histone acetylation modification." (PMID 27965534, 2016). "Furthermore, our results indicate that HDAC1 inhibition deteriorates the behavioral outcomes of rats with ischemia due to neurological severity and motor function deterioration." (PMID 34381129, 2021). "Moreover, the results revealed that the number and ratio of TUNEL-positive neurons increased in rats with ischemia, and HDAC1 inhibition further exacerbated the level of DNA damage in rats with ischemia, implying that HDAC1 inhibition can increase cell apoptosis." (PMID 34381129, 2021). "Administration of corin or vehicle (DMSO), at 10 mg/kg/day at 16- and 1-h pre-ischemia, did not result in biochemical renal injury in either HDAC1-/- or HDAC2-/- mice." (PMID 33907245, 2021). "HDAC1 and HDAC2 are localized mainly in the nuclei of neurons, astrocytes and oligodendrocytes, but their expression may change after ischemia." (PMID 31200484, 2019). "Interestingly, valproate, another HDAC inhibitor (HDAC1–3 and 8), is neuroprotective and anti-inflammatory in rodent models of TBI and ischemia." (PMID 29482641, 2018).
liver fibrosis (9 papers, 2013 to 2025). "Notably, p-C/EBPα-S193 positively regulates age-associated hepatic fibrosis by affecting the formation and function of C/EBPα-p300 and C/EBPα-HDAC1 complexes." (PMID 36299447, 2022). "Taken together, our findings show that LP340, the lead of a new generation of selective HDACi for HDAC1, 2 and 3, alleviates liver fibrosis either preventively or when given as therapy." (PMID 38828459, 2024). "Here, we examined whether LP340, the lead candidate of a new-generation of hydrazide-based HDAC1,2,3 inhibitors (HDACi), decreases liver fibrosis." (PMID 38828459, 2024). "A possible good candidate with joined relevance in the pathological process of kidney and liver fibrosis might be HDAC1, as previously discussed." (PMID 23281659, 2013). "Pirfenidone, but also LBH589, reduced significantly the protein expression of HDAC1, HDAC2, and of a ~66 kDa isoform of class-IIa-HDAC9, a HDAC comprising several alternatively spliced isoforms with profibrotic function in liver fibrosis." (PMID 30481203, 2018).
myeloid leukemia (9 papers, 2014 to 2024). A clonal proliferation of myeloid cells and their precursors in the bone marrow, peripheral blood, and spleen. "This study also found that patients with lower HDAC1 and higher Klf4 levels had better prognosis, making these proteins new potential diagnostic and prognostic markers and therapy targets for myeloid leukemia." (PMID 25341045, 2014). "By evaluating the effects of specific HDACs in human myeloid leukemia, we first found that the expression level of HDAC1 was negatively correlated with Klf4 expression and that patients with lower HDAC1 levels showed a better prognosis." (PMID 25341045, 2014). "Further studies suggested that the mechanism by which HDAC1 affects myeloid leukemia cells is mainly by regulating Klf4." (PMID 25341045, 2014). "Mechanistic analyses demonstrated that HDAC1 and Klf4 competitively bound to the promoter region of Klf4 and oppositely regulated Klf4 expression in myeloid leukemia." (PMID 25341045, 2014). "Further functional and mechanistic studies indicated that HDAC1 specifically targets Klf4 and that this interplay inhibits myeloid leukemia cell proliferation and cell cycle." (PMID 25341045, 2014). "In a mouse model, overexpression of SETBP1 in hematopoietic progenitors resulted in the development of myeloid leukemia characterized by reduced expression of RUNX1 due to deacetylation of histones in the gene promoter mediated by Histone deacetylase 1 (HDAC1)." (PMID 36499582, 2022). "MiDAC has been shown to contain protein subunits MIDEAS, HDAC1, HDAC2 and DNTTIP1 in myeloid leukemia K562 cells and human T lymphocyte CEM cells." (PMID 38781120, 2024). "HDAC1 and KLF4 interact with each other to regulate the proliferation of human myeloid leukemia cells." (PMID 36211454, 2022). "Dacinostat (LAQ824) is known to inhibit HDAC1 but is also reported as a potent HDAC inhibitor and was shown to be effective against myeloid leukemia cells in vitro and in vivo." (PMID 36077629, 2022). "HDAC1, ranked 29th by MUFFINN yet below 6000th by all three gene-centric methods in LAML samples, is a deacetylase, a chromatin modifying enzyme, and has been reported to be involved in myeloid leukemia cell proliferation." (PMID 27333808, 2016).
Cerebral ischemia (8 papers, 2018 to 2025). Restriction of arterial blood supply to the brain associated with insufficient oxygenation to support the metabolic requirements of the tissue. "Using a rat model of endothelin-1–induced focal cerebral ischemia, HDAC1 knockdown was achieved via stereotactic co-injection of HDAC1 siRNA." (PMID 41388741, 2025). "Our previous studies demonstrated that HDAC1 expression and enzymatic activity are significantly reduced following ischemic stroke in a rat model of brain ischemia." (PMID 41388741, 2025). "In the subacute phase, the decrease in TOPK levels was accompanied by the down-regulation of M2 surface markers and phosphorylation of HDAC1/HDAC2 following cerebral ischemia-reperfusion in vivo." (PMID 29896413, 2018). "Therefore, we attempted to synthesize K-560-related compounds in order to assess their inhibitory activities against HDAC1, 2, 3, 8 (Class I) and 6 (Class II) and ameliorating effects on in vitro cerebral ischemia and also to examine their SAR." (PMID 29362442, 2018). "We assessed the potency of these compounds as neuronal protective agents through measuring their toxicity degree to human neuroblastoma SH-SY5Ycells and cell viability in an in vitro model of cerebral ischemia, as well as their selectivity in HDAC1, 2, 3, 8 (Class I) and 6 (Class II) inhibition." (PMID 29362442, 2018). "The results of Co-IP showed binding of TOPK to HDAC1 and HDAC2 in brain tissues both under normal conditions and following brain ischemia-reperfusion, with increased binding over time and a significant interaction detected at 3 days for HDAC2." (PMID 29896413, 2018). "In cerebral ischemia–reperfusion injury, TOPK promotes the polarization of macrophages towards the M2 phenotype, exerting a neuroprotective effect by positively regulating M2 polarization of microglial cells/macrophages through the inhibition of HDAC1/HDAC2 activity." (PMID 40826334, 2025). "Moreover, TOPK co-localized with p-HDAC1 and p-HDAC2 by immunofluorescence, which was confirmed by the Co-IP analysis showing that TOPK binds to HDAC1 and HDAC2 in brain tissues both under normal conditions and following cerebral ischemia-reperfusion." (PMID 29896413, 2018).
Huntington disease (8 papers, 2014 to 2025). Huntington disease (HD) is a rare neurodegenerative disorder of the central nervous system characterized by unwanted choreatic movements, behavioral and psychiatric disturbances and dementia. "Accordingly, increased HDAC1 function is associated with neuroprotective effects against ischemia‐induced neuronal death and Huntington's disease in a Caenorhabditis elegans model." (PMID 32449313, 2020). "In tauopathy and Huntington’s disease, HDAC1 is selectively increased in vulnerable brain regions such as the cortex and hippocampus, which contributes to the neurodegeneration in those ailments." (PMID 30341976, 2018). "For instance, Hdac1 expression is upregulated in a mouse model for Huntington’s disease." (PMID 27803663, 2016). "This review will discuss evidence supporting the involvement of HDAC1 and HDAC3 in polyglutamine disorders, including Huntington’s disease, and the use of HDAC1- and HDAC3-selective HDAC inhibitors as therapeutic intervention for these disorders." (PMID 24865773, 2014).
rheumatoid arthritis (8 papers, 2010 to 2024). A chronic, systemic autoimmune disorder characterized by inflammation in the synovial membranes and articular surfaces. "Studies have shown that HDAC1 is highly expressed in synovial tissues of rheumatoid arthritis, which can promote synovial cell hyperplasia and inflammation." (PMID 35794630, 2022). "HDAC1 has been confirmed to be highly expressed in rheumatoid arthritis and is thought to play an important role in inflammatory diseases." (PMID 35794630, 2022). "Synovial fibroblasts from patient with rheumatoid arthritis have shown increased expression of HDAC1 when compared to those with osteoarthritis." (PMID 21346816, 2011). "HDAC1 is overexpressed in rheumatoid arthritis synovial fibroblast (RA-SF)." (PMID 38714604, 2024). "For example, in patients with rheumatoid arthritis, DNA hypomethylation of HDAC1 (histone deacetylase 1) and HDAC2 levels, hyperacetylation of histones H3 and H4, and hypomethylation of histone H3 at lysine 9 have been observed in synovial tissues." (PMID 27377127, 2016).
cutaneous T-cell lymphoma (7 papers, 2008 to 2023). "The study conducted by Marquard and collaborators in cutaneous T-cell lymphoma (CTCL) patients reported a high expression level of HDAC1, HDAC2, and HDAC6, and an association between the levels of HDAC2 and histone H4 acetylation and tumor aggressiveness." (PMID 30096875, 2018). "HDAC1 and HDAC2 are upregulated in DLBCL, peripheral T-cell leukemias, cutaneous T-cell lymphomas and NK/T-cell lymphomas and the expression of HDAC1 was found to be related to worse prognosis in patients." (PMID 38028538, 2023). "In cutaneous T-cell lymphoma, upregulation of HDAC1 and HDAC6 was detected as a result of excessive autocrine production of IL-15 driven by disruption of the Zeb1 transcription factor binding to the IL-15 promoter." (PMID 35887172, 2022). "Recently, we have shown that miR-34a can control miR-16 as well as p21 via targeting of HDAC1 and c-Myc in NSCLC and cutaneous T-cell lymphoma (CTCL)." (PMID 35453680, 2022). "Vorinostat (SAHA), the inhibitor of HDAC1, has been approved by the FDA as an effective drug for the treatment of cutaneous T cell lymphoma." (PMID 27869685, 2016). "Expression of HDAC1, HDAC2, HDAC6, and acetylated H4 (H4ace) in different subtypes of cutaneous T-cell lymphoma (CTCL) (n = 73)." (PMID 18671804, 2008).
endometriosis (7 papers, 2018 to 2025). The growth of functional endometrial tissue in anatomic sites outside the uterine body. "In summary, we believe that gut dysbiosis leads to the deficiency of n-butyrate, and causes an increased expression of HDAC-1 which plays a prominent role in epigenetic regulation in endometriosis." (PMID 38505548, 2024). "In patients suffering from endometriosis, immunohistochemical analysis confirmed a substantial expression of HDAC1/2 proteins, which varied depending on lesion localization." (PMID 37174627, 2023). "Our findings that n-butyrate inhibited HDAC activity and that HDAC activity is required for endometriotic cell growth are consistent with studies reporting elevated HDAC1 expression in lesions from women with endometriosis." (PMID 34593556, 2021). "A study investigating HDAC expression of endometriosis showed that levels of gene and protein expressions of HDAC1 and HDAC2 were higher in ectopic endometrium than in normal endometrium." (PMID 29780815, 2018). "HDAC1, HDAC2, HDAC3, Sirtuin 1, and Sirtuin 3, are the five most studied HDAC enzymes which seem to, at least partly, influence the pathophysiology of endometriosis." (PMID 37174627, 2023).
esophageal cancer (7 papers, 2013 to 2023). A primary or metastatic malignant neoplasm involving the esophagus. "The results showed that the overexpression of Per2 markedly increased the migration of esophageal cancer cells, which was abolished by transfected with empty plasmids, or knockdown of the HDAC1 gene, of knockdown the E-cadherin gene, respectively." (PMID 26898709, 2016). "We wondered if HDAC1 was involved in the Per2-repressed E-cadherin expression in esophageal cancer cells." (PMID 26898709, 2016). "Overexpression of Per2 markedly increased the migratory capacity of esophageal cancer cells, which was abolished by the inhibition of HDAC1." (PMID 26898709, 2016). "The inference is supported by our further experimental data; the presence of sodium butyrate (a HDAC1 inhibitor) markedly inhibits the migratory capacity of esophageal cancer cells." (PMID 26898709, 2016). "HDAC1 is involved in the inhibitory process of E-cadherin induced by Per2; blocking HDAC1 inhibits the migratory capacity of esophageal cancer cells." (PMID 26898709, 2016). "The expression levels of HDAC1, HDAC2 and HDAC3 were significantly up-regulated in esophageal cancer specimens compared to normal specimens." (PMID 37171386, 2023). "Nanoliposomal quercetin combined with CD133 antiserum targeted CD44 and CD133 and decreased expression of NF-κBp65, histone deacetylase 1 (HDAC1), and cyclin D1, increased the expression of caspase-3 and E-cadherin in Eca109/9706 esophageal carcinoma cells." (PMID 37033601, 2023). "Our study showed that both tumor-specific histone methylation and higher expression levels of histone deacetylases HDAC1, HDAC2 and HDAC3 are involved in miR-497 downregulation in esophageal cancer cells, suggesting the epigenetic complexity of miRNA deregulation." (PMID 37171386, 2023). "The higher expression of PER‐2/per‐2 in metastatic oesophageal carcinoma cells inhibits the expression of E‐cadherin, while HDAC‐1 is involved in the inhibition of E‐cadherin induced by PER‐2 and blocks the ability of HDAC‐1 to inhibit the migration of oesophageal cancer cells." (PMID 31957271, 2020).
heart failure (7 papers, 2013 to 2025). Inability of the heart to pump blood at an adequate rate to meet tissue metabolic requirements. "-Exercise-induced HDAC4 fragments protect against heart failure.-HDAC1/HDAC2 reverse diabetic heart pathology." (PMID 40822014, 2025). "As previously demonstrated, cardiac-specific deletion of the mouse Hdac1 and Hdac2 genes evoked a strong heart failure phenotype, which is consistent with our finding." (PMID 30110327, 2018). "Our results showed increased activity and binding of HDAC1 to the Atp2a2 promoter region, indicating that it might be a causal factor of SERCA2a downregulation mediated by hypoacetylation during TAC-induced heart failure in mice." (PMID 30286210, 2018). "In this study, we demonstrated class I HDAC isoforms HDAC1 and HDAC2 are upregulated in cardiac fibroblasts as the animals progressed through heart failure." (PMID 25024745, 2014).
Hepatic steatosis (7 papers, 2007 to 2025). Steatosis is a term used to denote lipid accumulation within hepatocytes. "For example, HDAC1 stimulates angiogenesis in epithelial cells, an event associated with retinal disease and other age-associated pathologies, and generates hepatic steatosis in mice, a pathological condition associated with increased age, body weight, and fibrosis." (PMID 17578512, 2007). "Tributyrin inhibited HDAC1, enhanced the CPT1a expression, and improved hepatic steatosis in mice." (PMID 36077368, 2022). "The reduced HDAC1 activity or HDAC1 knockdown decreased the SREBP1 protein level and attenuated hepatic steatosis (NF-κB/HDAC1/SREBP1c)." (PMID 36077368, 2022). "The underlying molecular mechanism of sodium butyrate in preventing hepatic steatosis may be attributed to the activation of CaMKII‐CREB and inhibition of the HDAC1‐CREB signaling pathway via hepatic GPR41/43." (PMID 36382553, 2023). "Dietary fiber could also mitigate hepatic steatosis via the liver’s G-protein-coupled receptor (GPR) 41/43-calmodulin-dependent protein kinase II (CaMKII), histone deacetylase 1 (HDAC1)-cyclic adenosine monophosphate response element-binding protein (CREB) pathway." (PMID 38730369, 2024). "The beneficial effect of MS-275 in fatty liver might be mediated by inhibition of HDAC1/2 rather than HDAC3." (PMID 36077368, 2022). "A previous study demonstrated that HDAC1/2 bind to the fatty acid synthase promoter and induce deacetylation of H3K9 and H3K27, suggesting that HDAC1 may participate in the progression of fatty liver disease." (PMID 34925033, 2021). "Notably, although Sphk2 was not involved in chronic Dex-induced hepatic steatosis and hypertriglyceridemia, we cannot exclude the involvement of ERK1/2 and HDAC1/2 in this process." (PMID 40490140, 2025).
Hypertension (7 papers, 2019 to 2025). The presence of chronic increased pressure in the systemic arterial system. "We have proved, for the first time, the relationship between global H3K23/H3K36 hypoacetylation in association with HDAC1 up-regulation and the development of EDS/hypertension phenotype in OSA patients." (PMID 34667186, 2021). "Furthermore, obesity-related hypertension in high-fat diet-fed mice is associated with increased HDAC1 levels and histone H3 acetylation, and administration of the HDAC inhibitor valproic acid was shown to suppress the progression of hypertension." (PMID 40186651, 2025). "That demonstrated increased HDAC1 expression and decreased histone acetylation suggesting increased HDAC activity indirectly in the HFD-induced hypertension." (PMID 31655853, 2020). "In our current study, we found that MS-275, a class I HDAC-selective inhibitor (HDAC1, HDAC2, and HDAC3), lowered blood pressure, reduced blood vessel thickness, and inhibited inflammation in an Ang II-induced hypertensive animal model." (PMID 30830950, 2019). "HDAC1 binds to deacetylated c‐Myc at the renal angiotensinogen (Agt) gene promoter, upregulates Agt and ANG II levels, and participates in the pathogenesis of obesity‐related hypertension." (PMID 40497340, 2025). "In hypertension induced by an HFD, HDAC1 and HDAC2 are activated, leading to nuclear accumulation." (PMID 40497340, 2025). "In summary, HDAC5 plays an important role in the early pathogenesis and vascular remodelling of ANG II‐induced hypertension, HDAC6 affects vascular relaxation function, while HDAC1 and HDAC2 regulate the transcription of genes related to blood pressure regulators." (PMID 40497340, 2025).